KRT5 (keratin 5)
Diseases named in the same sentence as KRT5 in open-access papers (continued):
Sharing a sentence is not in itself a finding about the gene and the disease.
tumor (continued). "Additionally, to assess the contamination of tumour cells in metastatic samples, we examined the expression of oesophageal epithelium genes (KRT5, KRT19, EPCAM and SOX4) and found almost no cells that expressed these genes." (PMID 36650114, 2023). "Immunohistochemical staining showed that the tumor cells were positive for thyroid transcription factor 1 (TTF-1) and CEA, but negative for prostate-specific antigen (PSA), Wilms tumor 1 (WT-1), p40, cytokeratin 5/6 (CK5/6), CK7, CK20 and anaplastic lymphoma kinase (ALK)." (PMID 38142271, 2023). "Of interest, six proteins (FOXA1, ERBB2, MAPT, NAT1, PHGDH, KRT5) and one protein (PHGDH) overlapped between PAM50 and the differentially expressed proteins between basal-like and luminal-like subtypes in microdissected tumor epithelium and stroma, respectively." (PMID 37349288, 2023). "The tumor center was characterized by a higher abundance of transferrin (TF), endoplasmic reticulum oxidoreductase 1 (ERO1)-like protein (ERO1A), EH domain-containing protein 1 (EHD1), keratin 5 (KRT5), serpin H1 protein (SERPINH1), and lactate dehydrogenase A (LDHA)." (PMID 35512017, 2022). "However, we failed to observe any GFP+ tumour in Krt5 mice (0 out of 130 analysed tumours), suggesting that neither Basal cells from upper airways nor AT1 cells contributed to Eml4-Alk LUAD initiation." (PMID 35931677, 2022). "Moreover, miR-196a promoted tumor progression by down-regulation of SPRR2C, S100A9 and KRT5." (PMID 33289788, 2021). "For Wnt1-EarlyEx tumors, these two fractions accounted for only about 65% of the tumor, with the remaining 35% consisting of regions/cells that did not stain positive for either Krt5 or Krt8/18; the identify of these non-staining cell type(s) is unknown." (PMID 31213486, 2019). "The expression of KRT5 / KRT14 pairs is closely related to the intermediate phenotype of cells that undergo the epithelial-mesenchymal transition (EMT), which has a significant effect on tumor progression and metastasis because it helps to spread tumor cells throughout the body." (PMID 29377892, 2018). "Additionally, all parts of the tumour were negative to the specific myoepithelial markers cytokeratin 5/6 (CK5/6) and p63." (PMID 30185896, 2018). "However, these two basal/SCC‐like tumour categories do not differ in their KRT5, KRT14/FOXA1, GATA3 ratios, their defining characteristics, or their shifts to high CDH3 and lower CDH1 expression." (PMID 28195647, 2017). "Of the most significantly differential enrichment on H3K4me3 and/or H3K27ac marks between SCC and ADC tumours, we found much higher load of H3K27ac and H3K4me3 marks in the SCC tumour compared to the ADC tumour on the squamous genes Sox2, ΔNp63, Ngfr and Krt5/6." (PMID 28387316, 2017). "All four tumours were negative for KRT5/6 protein but positive for EGFR staining." (PMID 25633981, 2015). "Consensus clustering (using the same gene set) generated 2 sample groups that also broadly recognized the KRT5-positive and -negative tumors; the exception was the KRT5-positive tumor (D19) that was intermediate between the two groups by all statistical assays." (PMID 22347416, 2012). "Moreover, the BC subtype transcriptome analysis indicates that the original donor BC tumor tissue expresses only a few genes related to the luminal/smooth muscle subtype (GATA3/DES), while the PDX cell line differentiated into a basal subtype (KRT5/6A and COL17A1)." (PMID 40801146, 2025). "However, due to the overly high cell density of the tumour nest and the limited IMC resolution, some adjacent tumour cells and infiltrated immune cells were recognised as epithelial–immune dual feature cells, such as Clusters 4 (KRT5+, KRT19+, CD20+ and CD79A+) and 14 (KRT5+, KRT19+ and LYZ+)." (PMID 37349991, 2023). "In contrast, genes with higher expression in HET/no pCR samples included basal cytokeratins (KRT5, KRT14, and KRT17), suggesting possible tumor subtype–related differences." (PMID 38300710, 2024).
tumor (continued). "Importantly, neither Krt5-driven expression of MCPyV LT nor co-expression of MCPyV-LT with Atoh1 or with sT and Atoh1 did alter the phenotype of the mice—in particular tumor growth in the Atoh1/sT setting—questioning the significance of LT with respect to tumor formation." (PMID 36672392, 2023). "EN1 is selectively overexpressed in TNBC tumours, either basal-like BCs or quintuple negative BCs (ER-, PR-, HER2-, Cytokeratin 5/6 (CK5/6) and EGFR-)." (PMID 35267409, 2022). "Using the tissue segmentation function, the intra-(tumor or epithelial) region was defined by cytokeratin-5 (CK5+ epithelial cells) and the peri-(tumor or epithelial) region in stroma comprised CK5− non-epithelial cells." (PMID 34617194, 2022). "Tumor samples with absent immunoexpression of GATA3, FOXA1 and CK5/6 showed significantly lower transcript levels of GATA3, FOXA1 and KRT5/KRT6A, respectively (p < 0.001, p = 0.0130, p < 0.0001 and p = 0.0278)." (PMID 32758253, 2020). "The majority of pure pTa HG/papillary pT1(a) HG samples exhibited a luminal-like phenotype, i.e., positivity for KRT20 and a lack of basal cytokeratin (KRT5/6 and KRT14) expression in tumor cells." (PMID 32445084, 2020). "One portion of the SCCL/Mes‐Inf cluster was negative for KRT5/KRT14 and FOXA1/GATA3, as well as for CDH3 expression, making it distinct from basal/SCC‐like tumours." (PMID 28195647, 2017). "No statistical correlation was found between KRT5 or KRT6 expression with patient age at diagnosis, tumor stage, tumor grade, or size of residual tumor after cytoreductive surgery in the TCGA dataset (data not shown)." (PMID 28147318, 2017). "In humans, tumours are considered basal-like if they are negative for nuclear ERα, PR and HER2 (triple-negative) but positive for KRT5/6 or EGFR." (PMID 25633981, 2015). "Most participants would not request additional tumour analyses (e.g. epidermal growth factor receptor (EGFR), cytokeratin 5/6, 14 and 17)." (PMID 22276059, 2011). "It must be noted that the triple-negative subtype defined in our study contains both array-defined basal-like tumor and unclassified subtypes, since we have not performed immunohistochemical staining for HER1 and cytokeratin 5/6." (PMID 18307763, 2008). "The basal-like tumours were defined as having no expression of ER and HER2; 98 of them did express epidermal growth factor receptor and/or cytokeratin 5/6." (PMID 17088909, 2006). "Immunohistochemical stains demonstrated positivity of the tumor with sex-determining region Y-box 10 (SOX10) and negative staining with smooth muscle actin (SMA), Cluster of Differentiation 10 (CD10), protein 40 (P40), cytokeratin 5/6 (CK5/6), and melanin." (PMID 40125165, 2025). "While Krt5 was positive, Sox2, a marker and driver of SCC, was negative in all samples, while positive cells were detected in basal cells of the trachea, suggesting a co-expression rather than squamous differentiation of tumor cells." (PMID 33738287, 2021). "The absence of an association of CDCP1 expression and copy number gains with clinicopathological features or the expression of a basal-like BC marker, such as cytokeratin 5/6, suggests that CDCP1 is already present in early-stage TNBCs, independent of the molecular phenotype of tumor cells." (PMID 27626701, 2016).
cancer (253 papers, 2006 to 2026). A tumor composed of atypical neoplastic, often pleomorphic cells that invade other tissues. "At necropsy, presumptive “luminal” tumors contain at least one cell subpopulation we call “luminobasal” that is ER−PR− and expresses cytokeratin 5 (CK5), a protein usually associated with basal-like cancers." (PMID 25475897, 2014). "Notably, HIST1H1D, PSMD2, ANXA2 and SPTAN1 overexpression was associated with elevated protein content in cancer tissues, whereas KRT5 has been rarely observed at the protein level in these tissues." (PMID 32252346, 2020). "KRT5+ cells form cancer organoids over successive passages, are tumorigenic in serial dilution xenograft assays, and are resistant to the antineoplastic agents, doxorubicin and cisplatin." (PMID 42111394, 2026). "KRT5 and TP63 are known epithelial and basal markers, and their overexpression has been implicated in pathways and lineages that drive carcinoma progression." (PMID 41362277, 2026). "Using these eight cancer types, we defined a set of 76 core basal genes, which include the classic markers KRT5, KRT6A/B/C, and DSG3." (PMID 38791964, 2024). "Through this analysis, we identified eight major cell types, namely B cell (CD79A), cancer cell (KRT5), cycling cell (MKI67), endothelial cell (VWF), fibroblast (COL1A1), mast cell (KIT), monocyte/macrophage (CD14) and T cell (CD3D)." (PMID 38279519, 2024). "Dysregulation of KRT5, a basal keratin marker, has been reported to promote cancer invasion and metastasis." (PMID 37365152, 2023). "The study found that 19/21 cases expressed GATA3 in over 25% of the cancer cells, and five of these 19 co-expressed KRT5/6." (PMID 35406463, 2022). "Keratin 5 (KRT5), located at chromosome 12, also had been certified to be involved in cancer progression." (PMID 35302673, 2022). "Histopathological analysis confirmed the presence of large metastatic lesions in the brains, and IF staining showed specific expression of the basal cancer subtype marker KRT5 as well as the proliferation marker Ki67." (PMID 34741115, 2021). "Histopathological analysis confirmed the presence of metastatic lesions in the lungs, and IF staining showed specific expression of the basal cancer subtype marker KRT5." (PMID 34741115, 2021). "Inspection of parental tumors revealed the presence of cytokeratin 5/6 positive cancer cells within luminal carcinomas as well, a result in line with previous observations." (PMID 33371412, 2020). "In Pten;Tgfbr2 tumors, the invasive cancer was highly proliferative and was largely Krt5-high and Krt8-low, whereas fewer cells stained positive for Ki67 in intact HGPIN ducts that were luminal." (PMID 29782499, 2018). "KRT5 is a marker of stem or progenitor cells and can be found in basal-like carcinoma subtypes, often with squamous/sarcomatoid histological features, whereas KRT20, a marker of superficial umbrella cells, is enriched in luminal subtypes." (PMID 30380731, 2018). "In this study, we report that human oncogenic KRAS driven by the zebrafish krt5 or gfap promoter induces malignant tumors of the nervous system." (PMID 25644510, 2015). "Coexpression of keratin 14, a basal cell marker of squamous and glandular epithelia, keratin 5 and involucrin are reported to represent a stem cell or progenitor cell phenotype in cancer cells." (PMID 26807202, 2015). "qPCR analysis of a number of reported miR196a targets in other cancers, KRT5, ANXA1, S100A9 and HOXC8, was conducted." (PMID 25860510, 2015). "Basal-like cancer cells commonly express some of the basal cell markers such as cytokeratin 5 (CK5) and 17 (CK17), as well as caveolin-1, EGFR, B-crystallin, P-cadherin, and c-KIT." (PMID 20979652, 2010).
cancer (continued). "This cluster expressed genes specific to basal-like and normal-like cancer subtypes, including keratin-5, keratin-17, and GGH." (PMID 17054791, 2006). "Cytokeratin 5/6 (CK5/6)-positive cancer cells were found in patients #1, #2, #3, and #5." (PMID 40551232, 2025). "And, ZNF750 expression positively correlated with the KRT5 level in most cancer types." (PMID 37365152, 2023). "Furthermore, pancancer analysis of 33 cancer types in TCGA revealed that TRIM29 expression positively correlated with ZNF750 and KRT5 levels in most cancer types." (PMID 37365152, 2023). "However, combined antibodies for cytokeratin 5 and 6 are widely used to identify basal-like subtypes in several cancer types." (PMID 36971797, 2023). "Stromal cells (or cancer-associated cells) included endothelial cells (PECAM1/CD31+ and MMRN1+), fibroblasts (COL6A1+, COL1A1+, THY1+, and DCN+), epithelial cells (LAMC2+, KRT5+, and KRT14+), and unassigned name cells (high heat shock proteins expression), suggesting that they were cancerous cells." (PMID 35742914, 2022). "We then checked the expression of the canonical cell-type markers: cancer/epithelial cell marker genes (Cdh1, Krt18, and Krt5); mesenchymal cell marker genes (Col1a1, Col1a2, and Col3a1); immune cell marker genes (Ptprc, Cd68, and Csf1r); and endothelial cell marker genes (Pecam1, Emcn, and Cdh5)." (PMID 34497807, 2021). "In addition, in PDOs, we observed an enrichment of basal cancer cells (cytokeratin 5/6 positive), which have also been detected in parental tumors." (PMID 33371412, 2020). "However, cytokeratin 5/6 positive organoids were also found in cultures derived from luminal cancers." (PMID 33371412, 2020). "When TAM-treated Krt5-CreERT2;TdtLSL mice (n = 4) were induced to form cancer with OHBBN and subsequently assessed for Epcam-CD49f expression we observed significant distribution of tomato positive cells to all gates (G1 = 31.4%, G2 = 39.5%, G3 = 20.5%, G4 = 6.9%, n = 4) (bottom)." (PMID 32439865, 2020). "The presence of cytokeratin 5/6 positive cells has been already reported for luminal carcinomas." (PMID 33371412, 2020). "However, in the Pten;Tgfbr2 tumors, a large proportion of the invasive cancer consisted of cells that were strongly positive for Krt5, with Krt8 cells intermixed." (PMID 29782499, 2018). "The upregulation of multiple lineage plasticity genes, including basal (Trp63, Krt5 and Krt14), metastasis (Snai2, Tgfb1 and L1cam), and stemness (Sox2, Mecom and Sox6) markers was induced by LKB1 loss, further supporting the enhanced cancer cell state plasticity by LKB1 loss." (PMID 39743630, 2025). "Thus, the effects of KRT5 on cancer are regulated by multiple mechanisms." (PMID 37671092, 2023). "In addition, we also found that ZNF750 could directly bind the promoter and promote the expression of KRT5, dysregulation of which could promote cancer invasion and metastasis." (PMID 37365152, 2023). "We searched for other potential overlaps and found that CXCL2, LIF, UBE2C, KRT5, ICAM1, and CXCL8 were significantly upregulated in STIC lesions identified in patients with cancer compared with adjacent normal epithelium." (PMID 40689422, 2025). "Subsequently, the LUAD marker genes NAPSA, NKX2-1, the LUSC marker genes TP63, KRT5, as well as EPCAM and MET were adopted to identify the cancer cell clusters." (PMID 38382091, 2024). "We therefore evaluated the expression of a panel of epithelial (KRT5, 7, 8, 18, and CDH1), mesenchymal (VIM, FN1, SNAI1, TWIST1, COL1A1, and PRRX1), and cancer stem cell (ALDH1A2, ALDH7A1, CD44, and CCND1) markers in all samples." (PMID 36980717, 2023).
cancer (continued). "While we were most interested in the cancerous squamous epithelial cells, the number of CECs (MUC5B, WFDC2) was larger than that of the cancer cells (TP63, KRT5, CDKN2A)." (PMID 35986392, 2022). "We found that the cancer subtype markers (GRP, CHGB, NEUROD1, and CHGA for NET; KRT5, DSC3, KRT6B, TP63, and KRT6A for SCC; and NKX2-1, KRT7, NAPSA, and MUC1 for ADC) were specifically expressed in the corresponding cancer subtypes." (PMID 35962452, 2022). "Immunofluorescence (IF) staining for the epithelial cell markers cytokeratin 5 and cytokeratin 7 and the transcription factor GATA3 was performed to characterize the three cancer organoid models." (PMID 35805961, 2022). "Fine needle aspiration biopsy of the axillary lymph node confirmed high-grade carcinoma based on the morphologic features and positive staining for epithelial markers (keratin AE1/AE3, keratin 5/6, keratin 7), GATA 3, and p63." (PMID 35444869, 2022). "The genes selected included epithelial (KRT5, CDH1, EpCAM), mensenchymal (VIM, SNAI1, TWIST), stem (ALDH1A1, PROM1), breast specific (ESR1, PALB2) and other genes related to cell cycle or other cancer pathways (CCND1, CTNNB1, Ki67, etc.)." (PMID 34071445, 2021). "For example, KRT5, KRT14, and KRT17 overexpression are related to poor survival across different types of cancers, especially breast cancers." (PMID 33441834, 2021). "We observed bimodal gene expression in columnar-like and squamous-like cancers, including MUC5B, KRT5 and CSTA, that differentiates ADC from SCC." (PMID 33462395, 2021). "hsa-miR-342-3p was negatively correlated with downregulated gene targets such as ZNF462 and NCOA7, and hsa-let-7b/c were anti-correlated with predicted targets KRT5 and GABBR2, with known activities in the cancer pathways." (PMID 32182819, 2020). "We were able to establish a patient-derived xenograft model with confirmed basal phenotype based on positive KRT-5 expression with mosaic expression of ROR1 in cancer cells." (PMID 31137681, 2019). "Hypomethylation was found in both KRT5 and MMT7 genes in cancer, in concordance with high gene expression in cancers." (PMID 31569550, 2019). "By inspecting the human exitron list, we found that EIS affects several cancer-related genes: the cancer marker genes BMI1, KRT5, and MUC1 and the genes involved in cell adhesion (CSF1), migration and metastasis (ZEB2 and KLF17)." (PMID 25934563, 2015). "Accordingly, we investigated expression profiles of cells within clusters 1 and 2 and found that 275 genes were expressed significantly in these cells compared with cells in other clusters, including SOX9, KRT5, a basal marker, and KIT, which is often overexpressed in tuft cell-like cancers." (PMID 37179317, 2023). "Such classification is achieved based on genomic and transcriptomic analyses, which point to differential expression of specific markers among tumors: the basal cytokeratins KRT5/KRT6A and KRT14, as hallmarks of basal BlCa, and the luminal markers FOXA1 and GATA3, as hallmarks of luminal cancer." (PMID 32758253, 2020). "These were chosen based on their gene expression patterns in cancer according to the literature survey: KRT5 and MMP7 for increased gene expression in cancer, KCNH2 for ambiguous expression in cancer, and CYP21A2 for unknown expression in BC." (PMID 31569550, 2019). "AR was present at a lower level in the Krt5 positive invasive cancer, and was clearly absent from stromal cells." (PMID 29782499, 2018). "As a control for our analysis, HeLa cancer cell line expressed cytokeratin 5/8, 18 and 19, but not cytokeratin 13, in consistence with the reported results in HeLa cell line." (PMID 27344169, 2016). "Mesothelial cells are generally positive for calretinin, thrombomodulin, cytokeratin 5/6, WT1, D2-40, vimentin, HBME-1 and CD44H, while polyclonal and monoclonal carcinoembryonic antigen, Ber-EP4, Leu-M1, CA-125, B72.3, PAX8, MOC 31, CA19-9 and ER are the most common markers of carcinoma." (PMID 34068638, 2021).